SLC7A11 (solute carrier family 7 member 11)
Diseases named in the same sentence as SLC7A11 in open-access papers (continued):
Sharing a sentence is not in itself a finding about the gene and the disease.
cancer (continued). "In the next section, we will further discuss how our mechanistic understanding of SLC7A11-induced nutrient dependency can help inform therapeutic strategies to target SLC7A11 in cancer." (PMID 33000412, 2021). "It is a well-characterized specific inhibitor of SLC7A11-mediated cystine transport and has been shown to inhibit the growth, invasion, and metastasis of several cancer types." (PMID 34162423, 2021). "Subsequent studies revealed that SLC7A11 inhibition can induce apoptosis in cancer cells under different contexts." (PMID 33000412, 2021). "Genomic depletion of OTUB1 gene dramatically downregulates SLC7A11 expression and sensitizes cancer cells to ferroptosis." (PMID 34485285, 2021). "In contrast, cancer cells with SLC7A11 overexpression increased reliance on glucose and glutamine dependency, presenting potential metabolic vulnerabilities." (PMID 34761566, 2021). "There is also a complex connection between aberrant metabolism and SLC7A11 cancer‐promoting performance." (PMID 34761566, 2021). "RT-PCR assays revealed that TPL suppressed the mRNA levels of NRF2, SLC7A11 in all these three cancer cell lines in a dose-dependent manner." (PMID 34108030, 2021). "The cystine/glutamate antiporter SLC7A11 (also commonly known as xCT) functions to import cystine for glutathione biosynthesis and antioxidant defense and is overexpressed in multiple human cancers." (PMID 33000412, 2021). "For example, this model would predict that SLC7A11 overexpression should promote glycolytic flux and that SLC7A11high cancer cells should be sensitive to glycolysis inhibitors." (PMID 33000412, 2021). "We will also explore the metabolic underpinnings of SLC7A11-induced nutrient dependency in cancer cells." (PMID 33000412, 2021). "SLC7A11 (xCT) was identified as a molecule required for the maintenance of cancer stem cells (CSCs)." (PMID 34194623, 2021). "Fully understanding the regulation mechanism of SLC7A11 is helpful to find an effective target for cancer therapy." (PMID 34162423, 2021). "As a critical modulator of intracellular redox balance, targeting SLC7A11 is considered a promising therapeutic opportunity for cancer treatment." (PMID 34722314, 2021). "Especially, the elevated expression of SLC7A11 in selenophilic cancer cells allows for the increased import of cystine, which is reduced to cysteine and then exported." (PMID 33499222, 2021). "As detailed in a later section, SLC7A11 promotes glucose dependency, leading to the exquisite vulnerability of cancer cells with high SLC7A11 expression (SLC7A11high) to glucose starvation." (PMID 33000412, 2021). "Recent studies have demonstrated that SLC7A11 plays diverse functional roles, including the regulation of therapeutic resistance in cancer." (PMID 34446045, 2021). "SLC7A11 is a critical factor of the cystine-glutamate antiporter, and widely participates in the multiple biological processes of cancer development." (PMID 34177591, 2021). "Several studies have also revealed that SLC7A11 plays vital roles in glutamine metabolism and regulates the glucose and glutamine dependency of cancer cells." (PMID 34938318, 2021). "TGF-β1 released by macrophages can promote cancer cells ferroptosis by activation of the SMAD-related signaling to inhibit the expression of SLC7A11." (PMID 34796174, 2021).
cancer (continued). "Many cancer cells upregulate SLC7A11 levels to enhance their capability to obtain extracellular cystine." (PMID 33000412, 2021). "In summary, our data suggest a novel anti-cancer mechanism of metformin in which metformin induces ferroptosis by repressing UFMylation of SLC7A11." (PMID 34162423, 2021). "Mechanically, radiotherapy can activate Ataxia-Telangiectasia mutated gene (ATM) to produce IFNγ and synergizes with immunotherapy-activated CD8+ T cells to suppress SLC7A11 expression in cancer cells." (PMID 34796174, 2021). "In mitochondria stress conditions, cancer cells upregulate some enzymes that are associated with glutathione (GSH) synthesis and amino acid transporters, including xCT (SLC7A11)." (PMID 34572286, 2021). "Mechanically, interferon γ (IFNγ) secreted by cytotoxic CD8+ T-cells induces ferroptotic cell death in cancer cells, through downregulation of system xc− subunits (SLC7A11 and SLC3A2)." (PMID 34742351, 2021). "The SLC7A11 functions to import cystine for glutathione biosynthesis and antioxidant defense and is overexpressed in multiple human cancers." (PMID 34722314, 2021). "A recent article published in Cell Research also pointed out that ionizing radiation (IR) induced an adaptive response involving SLC7A11 or GPX4 induction that promoted cancer cell survival." (PMID 34040532, 2021). "The enhanced stability of SLC7A11 by OTUB1 was supported by the cancer stem cell marker, cluster of differentiation 44 (CD44)." (PMID 33499222, 2021). "Among these cancer types, the SLC7A11 expression in COAD, UCEC, and STAD is also positively associated with MSI." (PMID 34938318, 2021). "In conclusion, this pan-cancer level bioinformatic study systematically elucidated the role of intra-tumoral expression of SLC7A11 in the prognoses, drug resistance, and potential immunotherapeutic response of patients with cancer." (PMID 34938318, 2021). "We show here that inhibition of MRP1 or xCT/SLC7A11 synergizes with APR‐246 to induce cancer cell death by increasing intracellular drug availability and by altering cellular redox status." (PMID 33314700, 2021). "A pan-cancer analysis on the association of CALU with HSPA5, GPX4 and SLC7A11 further confirmed the potential involvement of CALU in the regulation of ferroptosis." (PMID 34150647, 2021). "Correspondingly, it is well established that SLC7A11 promotes drug-, chemo-, and radio-resistance in cancer cells." (PMID 33000412, 2021). "Single-cell sequencing method revealed the SLC7A11 was majorly expressed in cancer cells and mononuclear cells." (PMID 34938318, 2021). "A recent study showed that the better survival of cancer cells under higher density is at least partly achieved by downregulation of SLC7A11 levels." (PMID 33000412, 2021). "Inhibition of GCLC leads to apoptotic cell death in ARID1A-deficient cancer cells, and the vulnerability of ARID1A-deficient gastric cancer cells to GSH inhibition is caused by decreased GSH synthesis due to diminished SLC7A11 expression." (PMID 34671561, 2021). "Recently, a study published in Nature Cell Biology has shown an increase in Slc7a11 mediated CySS uptake is important in maintaining redox balance, but it comes at a considerable cost for cancer cells." (PMID 34203453, 2021). "SLC7A11, the major transporter for the exchange of extracellular cysteine and intracellular glutamate, protects cancer cells from apoptosis and promoting tumor development by improving the synthesis of GSH." (PMID 33849550, 2021). "Hence, we speculated SLC7A11 is associated with the immune microenvironment of cancers." (PMID 34938318, 2021). "In short, our study demonstrates the function and mechanism of metformin in regulating ferroptosis in cancer cells through SLC7A11 UFMylation." (PMID 34162423, 2021).
cancer (continued). "CD8+ T cells secrete interferon gamma, regulate SLC3A2 and SLC7A11 expression, and promote cancer cell lipid peroxidation and ferroptosis." (PMID 34804371, 2021). "Microenvironment-dependent inhibition of NMD has been shown to promote also the expression of SLC7A11 which can protect cancer cells from oxidative stress." (PMID 34852841, 2021). "SLC7A11 is overexpressed in multiple types of cancer, and suppressing transcription and protein expression of SLC7A11 can effectively induce ferroptosis in cancer cells." (PMID 34539740, 2021). "By actively importing insoluble CySS there is a potential toxic effect; thus, cancer cells with elevated Slc7a11 must rapidly reduce insoluble CySS to soluble Cys to prevent toxicity." (PMID 34203453, 2021). "As critical modulator of intracellular redox balance, targeting SLC7A11 is considered a promising therapeutic opportunity for cancer treatment." (PMID 34074015, 2021). "At the transcriptional level, SLC7A11 is upregulated in cancer cells by transcription factors, such as nuclear factor erythroid 2-like 2 (NFE2L2/NRF2) and activating transcription factor 4 (ATF4)." (PMID 34742351, 2021). "To further explore the function of SLC7A11 in cancer progression, we analyzed the influence on cell proliferation after the knockdown or knockout of SLC7A11 by either CRISPR or RNAi methods." (PMID 34938318, 2021). "The cystine/glutamate antiporter solute carrier family 7 member 11 (SLC7A11) is the core target for ferroptosis regulation, the overexpression of which dictates downregulated sensitivity to ferroptosis in cancer cells." (PMID 34938318, 2021). "As extensively discussed in previous sections, SLC7A11-mediated cystine uptake is critical for cancer cells to suppress ferroptosis and to maintain redox homeostasis and biomass incorporation." (PMID 33000412, 2021). "Conversely, to gain resistance to ferroptosis, cancer cells show a tendency to upregulate SLC7A11 expression following IR treatment." (PMID 34249928, 2021). "In colorectal CSCs, knockdown or inhibition of SLC7A11 significantly and specifically kills cancer cells and thus attenuates chemoresistance in CRC." (PMID 34568341, 2021). "Studies have shown that regulating the expression of SLC7A11, the functional subunit of system Xc−, affects system Xc− activity and ferroptosis sensitivity in cancer cells." (PMID 33731703, 2021). "Despite the accumulating evidence on the relationship between NRF2 and SLC7A11 expression, in addition to their effect on radioresistance in various types of cancers, the effect of SLC7A11 and NRF2 on radiosensitivity in ESCC remains to be elucidated." (PMID 34446045, 2021). "And overexpression of SLC7A11 significantly reversed the anti-cancer effect of metformin and the upregulation of GSH." (PMID 34162423, 2021). "Currently, there are small molecule inhibitors targeting SLC7A11, such as sorafenib, sulfasalazine, etc., which can play a therapeutic role in many cancers by inhibiting SLC7A11 activity." (PMID 35360452, 2021). "When a variety of cancer cell lines were grown in the presence of high levels of cystine, the glutamate/cystine antiporter xCT/SLC7A11 led to a depletion of glutamate in cells, which was ameliorated via glutaminolysis." (PMID 35028610, 2021). "Radiotherapy has been described to induce ferroptosis in preclinical cancer models and it synergizes with immunotherapy in the suppression of SLC7A11." (PMID 34485382, 2021). "A recent study claimed that the combination of immunotherapy and radiotherapy suppresses SLC7A11, thus this combinatorial treatment modality promotes ferroptosis in cancer cells." (PMID 33672990, 2021). "Accordingly, deficiencies in a host of NRF2 targets, including GPX4, SLC7A11 and FTH1/FTL, are also capable of predisposing cells to succumb to proferroptotic agents in many cancer types." (PMID 35118067, 2021).
cancer (continued). "This study systematically established the unfavorable role of SLC7A11 for longer survival, decreased new events, and potential response to immunotherapy in several cancers." (PMID 34938318, 2021). "It has been demonstrated that SLC7A11 confers resistance to ferroptosis in cancer cells by importing cystine for the synthesis of GSH and indirectly relieving lipid ROS stress by activating the essential enzyme GPX4 to reduce lipid hydroperoxides." (PMID 34568075, 2021). "The cystine/glutamate antiporter SLC7A11 (or xCT) imports cystine for glutathione biosynthesis and antioxidant defense and is overexpressed in a variety of human cancers." (PMID 34446045, 2021). "In the present study, we found that nucleotides, fatty acids, and glycine/serine/threonine metabolisms, which provide the necessary nutrients required for cancer cell proliferation, were all enriched in the high SLC7A11 expression group." (PMID 34761566, 2021). "Overexpression of SLC7A11 results in a cancer stem cell phenotype that contributes to severe chemoresistance." (PMID 32322334, 2020). "Instead, OTU deubiquitinase ubiquitin aldehyde binding 1 (OTUB1) directly interacts with SLC7A11 and stabilizes SLC7A11 by deubiquitinating SLC7A11, and this interaction is tightly regulated by the cancer stem cell marker CD44." (PMID 33294126, 2020). "A significant positive correlation was observed between the gene expression of SLC7A11 and insensitivity to vorinostat in a panel of 744 cancer cell lines (Pearson correlation = 0.275, Spearman correlation score = 0.290, p < 0.001)." (PMID 32235498, 2020). "Next, we systematically correlated sensitivity data (determined by AUC) of the small-molecule compounds (n = 481) with SLC7A11 gene expression across the entire cancer cell line cohort (n = 659)." (PMID 33167414, 2020). "A very recent study has reported that ARID1A regulates the glutathione metabolism through an increased transcription of SLC7A11, so that the inhibition of glutathione metabolism increases ROS level and induces apoptosis in cancer cells." (PMID 32763516, 2020). "The exchange has special significance in cancer cells which often overexpress the corresponding transporter SLC7A11 to increase the intracellular transport of cystine for glutathione biosynthesis (and references therein)." (PMID 32466567, 2020). "Potential NK cell dependence on cystine importer SLC7A11 expression would make them sensitive to glucose deprivation via disulfide accumulation, already a noted vulnerability in cancer cells." (PMID 33042135, 2020). "Mechanistically, phosphorylation of BECN1 at Ser90/93/96 through AMP-activated protein kinase (AMPK) promotes ferroptosis by binding to SLC7A11 and directly blocking the activity of system Xc-, contributing to cancer cell death." (PMID 33204324, 2020). "In a later study, NRF2 and SLC7A11 expression was found to be positively correlated across 947 cancer cell lines from the CCLE dataset, especially within 59 different BC cell lines." (PMID 32106613, 2020). "A recent study demonstrated that the NRF2-Keap1 pathway plays a critical role in cancer cell proliferation and lowering ferroptosis via up-regulating SLC7A11 and amplifying glutamate secretion." (PMID 33204324, 2020).
cancer (continued). "SLC7A11 is frequently overexpressed in different types of human cancers, including colorectal, liver and kidney cancers." (PMID 33182266, 2020). "Overexpression of the cancer stem cell marker CD44 increases the stability of SLC7A11 by promoting the interaction between SLC7A11 and OTUB1." (PMID 32516941, 2020). "Inhibition of SLC7A11 by erastin also increased the sensitivity of cisplatin in cancer cells, suggesting the combination of erastin and chemotherapeutical reagents can be sufficient for cancer therapy." (PMID 31921655, 2019). "As the SLC7A11 gene within the enzalutamide-stimulated gene network plays an important role in promoting cancer growth and metastasis, we also validated SLC7A11 expression." (PMID 31501863, 2019). "During ER stress, ATF4 is selectively translated to promote the expression of molecules that favor the adaptive survival of cancer cells such as SLC7A11/xCT." (PMID 31519193, 2019). "In cancer cells, SLC7A11 mediates the efflux of intracellular glutamate, thereby rendering them metabolically less adaptable and more reliant on glucose for survival." (PMID 31470592, 2019). "The amino acid transporter SLC7A11 in expressed in various cancers, and supports cancer cells in detoxifying reactive oxygen species (ROS)." (PMID 31261735, 2019). "Recent studies have unexpectedly revealed that SLC7A11 also plays critical roles in glutamine metabolism and regulates the glucose and glutamine dependency of cancer cells." (PMID 29764521, 2018). "Overall, a series of recent studies have identified an unexpected role of SLC7A11 in promoting cancer cell dependency on either glucose or glutamine." (PMID 29764521, 2018). "This review discusses the recent literature to understand the roles of SLC7A11 at the crossroads of reactive oxygen species (ROS) mitigation and nutrient dependency of cancer cells." (PMID 29764521, 2018). "Recent studies have indicated that NRF2 and ATF4 regulate cancer cell dependency on either glucose or glutamine through SLC7A11." (PMID 29764521, 2018). "It has been shown that supplementation of αKG in cultures of cancer cells overexpressing SLC7A11, which have lower intracellular αKG levels, abrogates glucose starvation-induced cell death." (PMID 29764521, 2018). "For example, upregulation of SLC7A11 in neuronal and cancer cell lines confers resistance to oxidative stress." (PMID 29764521, 2018). "Unexpectedly, various lines of experimental evidence, including cell line correlations, SLC7A11 overexpression, and SLC7A11 inactivation by knockdown or pharmacological inhibition, all indicate that SLC7A11 promotes cancer cell death under glucose starvation." (PMID 29764521, 2018). "For example, the master antioxidant transcription factor NRF2 can also regulate the expression of SLC7A11 at the transcriptional level, and NRF2 has been implicated as a key player in protecting cancer cells against ferroptosis." (PMID 29695998, 2018). "Conversely, blockade of conversion from glutamate to αKG in cancer cells with SLC7A11 knockdown, which have higher intracellular αKG levels, re-sensitizes these cells to glucose starvation." (PMID 29764521, 2018). "Further experiments validated that SLC7A11 inactivation inhibits cancer cell death under glucose starvation, whereas its overexpression promotes such cell death." (PMID 29764521, 2018). "We focus on SLC7A11 functions in the context of cancer biology in this review and refer to additional reviews discussing SLC7A11 functions in other pathologies and diseases." (PMID 29764521, 2018). "Conversely, it has been shown that inactivation of SLC7A11 by either small interfering RNA or pharmacological inhibition by sulfasalazine sensitizes cancer cells to proteasome inhibition." (PMID 29764521, 2018). "Increased expression of SLC7A11 is observed in a variety of cancers where the transporter-assisted promotion of glutathione synthesis reduces oxidative damage and protects the cancer cells from apoptosis." (PMID 30558624, 2018).